CRP (C-reactive protein)
Diseases named in the same sentence as CRP in open-access papers (continued):
Sharing a sentence is not in itself a finding about the gene and the disease.
heart failure (continued). "This study was conducted to explore the diagnostic utility of NT-proBNP and CRP to diagnose heart failure in patients presenting with acute hypoxemic respiratory failure." (PMID 32181077, 2020). "Researchers have found that higher circulation CRP level is associated with increased risks of cardiovascular diseases, including cardiomyopathy, myocardial infarction, heart failure and AF." (PMID 31391207, 2019). "Higher levels of plasma CRP concentration, measured using a hsCRP assay, have been associated with more severe heart failure and independently associated with morbidity and mortality." (PMID 29573742, 2018). "Higher incidence of in-hospital deaths of human patients due to decompensated heart failure were found to be associated with higher CRP concentration, higher leukocyte and neutrophil counts and lower lymphocyte count, which supports our findings." (PMID 29573742, 2018). "The Val-HeFT study demonstrated a direct correlation between elevated levels of C-reactive protein and heart failure severity, and C-reactive protein predicts the risk of death and early readmission in acutely decompensated heart failure." (PMID 29354115, 2017). "Elevated plasma CRP concentration is associated with an unfavourable outcome in acute MI and allows clinicians to stratify patients in terms of their risk of death and heart failure." (PMID 22973074, 2012). "Increased CRP concentrations were linked with an excess risk of death, heart failure, cardiac rapture, ventricular aneurysmal formation, and thrombus formation in MI survivors." (PMID 22446726, 2012). "As reported by several studies, elevated CRP levels after MI are associated with adverse clinical outcome, including cardiac rupture, heart failure, and cardiac death." (PMID 22973074, 2012). "High CRP concentrations have also been shown to be an independent risk factor for hospital readmission and mortality in patients with heart failure." (PMID 18838006, 2008). "SIRI may be a promising predictor for all‐cause mortality in the elderly with heart failure and statistically positively correlated with CRP." (PMID 41509129, 2026). "Specifically, the inflammatory markers hs-CRP, IL-1β, and IL-6 were significantly positively correlated, suggesting that these markers jointly participate in the inflammatory response associated with heart failure." (PMID 41333015, 2025). "A numerical rise in heart failure was associated with higher CRP levels - six (13.3%) in the high CRP group, seven (8.2%) in the moderate group, and three (4.3%) in the low group - affecting 16 (8%) of the patients overall, although this difference was not statistically significant (p = 0.10)." (PMID 41200636, 2025). "The association between CRP levels and heart failure was first reported in 1956." (PMID 40988759, 2025). "CRP concentrations at diagnosis were identified as markers of disease severity (odds ratio [OR] 1.006; 95%CI 1.001–1.011; p = 0.016), and the worsening of heart failure was associated with unfavorable outcomes (OR 3.105; 95%CI 1.397–6.902; p = 0.005)." (PMID 39330882, 2024). "This study observed that HIF-PH inhibitor therapy resulted in significant improvements in several clinical parameters associated with heart failure, including reductions in plasma B-type natriuretic peptide and C-reactive protein levels, along with an increased estimated glomerular filtration rate." (PMID 39768541, 2024). "Interestingly, high plasma levels of phenylalanine, as observed in the HFpEF rats, are associated with higher levels of C-reactive protein and inflammatory cytokines as well as higher mortality in patients with heart failure." (PMID 39143579, 2024). "Elevated c-reactive protein levels were associated with an increased risk of heart failure." (PMID 36882679, 2023).
heart failure (continued). "Although traditional epidemiological studies have revealed a link between CRP and the risk of heart failure, presumably supporting the hypothesis that there is a cause and effect connection, they may include limitations and various biases." (PMID 36882679, 2023). "In addition, many inflammatory markers associated with heart failure, including the erythrocyte sedimentation rate, hypersensitive C-reactive protein level, or WBC count, are strongly associated with RDW." (PMID 37206106, 2023). "The aim of this study was to evaluate a potentially causal relationship between CRP and heart failure, and the Mendelian randomization analysis was chosen because it mitigates the limitations of observational studies such as reverse causation and unmeasured confounding." (PMID 36882679, 2023). "Similarly, those with an elevated CRP level at 24 h post-admission, discharge and 1 month post-MI were all at a substantially increased risk of future heart failure hospitalisations." (PMID 34199975, 2021). "In the Framingham Heart Study, increased inflammatory markers, such as CRP, interleukin-6 and TNFα levels, were able to identify asymptomatic older subjects in the community who were at high risk for the future development of heart failure." (PMID 25142635, 2014). "It has became evident that heart failure is associated with subclinical inflammation which is in agreement with study demonstrating non-specific elevation in levels of some proinflamatory markers, such CRP, TNF-alfa, Il-6." (PMID 25400332, 2014). "CRP is a an indicator of systemic inflammation and is associated with risk of heart failure decompensation, whereas BNP is more specifically a marker of increasing hemodynamic load used in diagnosis and risk stratification among patients with congestive heart failure." (PMID 22588803, 2012). "Inflammation plays a pivotal role in the development of heart failure, potentially contributing differently to its various subtypes, with evidence highlighting a specific association between the interleukin-6 (IL-6)/C-reactive protein (CRP) pathway and the pathogenesis of HFpEF." (PMID 41169425, 2025). "However, the association between preoperative CRP level and early postoperative cardiac insufficiency remains unknown." (PMID 37063874, 2023). "Moreover, we depicted funnel plot of causal association for CRP on heart failure." (PMID 36882679, 2023). "However, residual confounding and reverse causality may remain alternative explanations for the strong association between CRP and fibrinogen with heart failure because of the inherent limitation of conventional observational studies." (PMID 34881299, 2021). "High sensitivity CRP is a biomarker that quantifies low grade systemic inflammation, in the absence of overt systemic inflammatory or immunologic disorders and has been used as a predictor of cardiovascular events, but has been also associated with diastolic dysfunction and heart failure in adults." (PMID 32664439, 2020). "The presence of chronic diseases, such as heart failure, and surgical procedures additionally contribute to the stimulation of the immune and sympathetic systems, causing inflammation manifested by high levels of C-reactive protein (CRP), elevated white blood cell count, and interleukin 6 (IL-6)." (PMID 32273868, 2020). "In our opinion, this observation indicates that PCT with its high sensitivity and specificity in diagnosis of bacterial bloodstream infection may be a more valuable indicator of bacterial translocation associated with advanced heart failure than such a versatile marker as CRP." (PMID 30245756, 2018). "Studies with human CHF patients have revealed that WBC and CRP may be implicated in the development of heart failure by the immune system acting as a modulator of myocyte injury and inflammatory reactions contributing to the structural and functional deterioration observed in failing human hearts." (PMID 29573742, 2018).
heart failure (continued). "Previous studies in heart failure and DCM populations have reported that elevated CRP levels are associated with reduced ejection fraction, higher NYHA functional class, and increased mortality." (PMID 41596517, 2026). "A recent study has demonstrated the real-time, noninvasive CRP monitoring using a wireless sweat sensor in both healthy individuals and patients with heart failure in a laboratory setting." (PMID 40856619, 2025). "As inflammation is a critical feature of heart failure, different inflammatory markers including C-reactive protein (CRP) or the interleukins (IL) 1, 6, and 18 represent interesting candidates as additional biomarkers." (PMID 40002917, 2025). "Persistently elevated CRP after ACS, even with modern therapies, indicates ongoing inflammation and predicts worse long-term prognosis, including higher mortality and heart failure risk." (PMID 41511355, 2025). "Our findings regarding heart failure patients and hs-CRP levels contradict the established literature." (PMID 40004724, 2025). "In clinical setting a positive significant correlation between sST2 and C-reactive protein (CRP) as inflammatory marker was demonstrated in heart failure patients with preserved ejection fraction." (PMID 41034674, 2025). "Compared to the lowest quintile, higher quintiles of neutrophil count, monocyte count, CRP, NLR, PLR, and SII were associated with a higher risk of heart failure; whilst higher quintiles of lymphocyte count and LMR were associated with a lower risk." (PMID 40234895, 2025). "pneumophila infections, especially in patients with high CRP levels, moderate hypophosphatemia, or heart failure." (PMID 41598997, 2025). "Clinical studies have shown that high CRP levels following MI were linked to adverse clinical outcomes such as LVR, heart failure development, and death." (PMID 39264503, 2025). "An elevated CRP/ALB ratio has also been associated with frequent and repeated hospital admissions, as well as an increased risk of developing severe heart failure." (PMID 40573094, 2025). "We identified age, NIHSS score, hyperlipidemia, hyperhomocysteinemia, cardiac insufficiency, CRP, WBC, NE%, Hb, FBG, PA, BNP and Na+ as key predictors, which were incorporated into a clinically practical nomogram for individualized AP risk prediction." (PMID 40529443, 2025). "Blood tests revealed an elevated white blood cell count (WBC) of 13,250/μL, C-reactive protein (CRP) of 10.14 mg/dL, and N-terminal pro-B-type natriuretic peptide (NT-proBNP) of 5,413 pg/mL, indicating an inflammatory response and possible heart failure." (PMID 40689011, 2025). "Higher CRP levels post-AMI are significantly associated with adverse outcomes, including early and late clinical events, cardiogenic shock, and heart failure." (PMID 40649166, 2025). "CRP concentration is a strong predictor of the occurrence orexacerbation of heart failure events in patients with heart failure and those atrisk." (PMID 40776958, 2025). "This is evidenced by the correlation between RDW and elevated acute phase reactants such as erythrocyte sedimentation rate (ESR), C-Reactive Protein (CRP), and interleukin- 6 in both the general adult population and heart failure patients." (PMID 41466195, 2025). "CANTOS suggested reductions in heart failure hospitalization, and anakinra lowered NT proBNP in high CRP ACS, supporting broader endpoints." (PMID 41302946, 2025). "As frequently observed in patients with heart failure, the mean levels of C-reactive protein were significantly higher in patients with elevated DYRK1B expression levels." (PMID 40002350, 2025). "Heart failure incidence increased with higher CRP levels - six (13.3%) in the high CRP group, seven (8.2%) in the moderate group, and three (4.3%) in the low group - but this difference was not statistically significant (p = 0.10)." (PMID 41200636, 2025).
heart failure (continued). "The correlation between CRP levels and EF suggests that elevated CRP levels may be associated with impaired heart function, which aligns with the understanding that inflammation plays a crucial role in cardiovascular dysfunction, particularly in conditions such as heart failure." (PMID 40599146, 2025). "The significance of C-reactive protein as the primary predictor corresponds with accumulating evidence regarding inflammation's contribution to cardiac failure advancement and readmission probability." (PMID 41573510, 2025). "The review further examines various inflammatory biomarkers that have been implicated in heart failure, such as cytokines (including TNF-α and IL-1) and C-reactive protein (CRP)." (PMID 40710370, 2025). "They concluded GDF-15 played a significant role in evaluating mortality from heart disease, and C reactive protein was identified as a predictor for heart failure." (PMID 39781722, 2025). "Given that albumin levels can be modified by inflammation and hydration, future studies should include analysis of inflammatory markers (e.g., CRP) to better understand the interaction between nutritional status and the course of heart failure." (PMID 40077630, 2025). "The conclusion drawn was that GDF-15 played a significant role in evaluating mortality from heart disease, and C reactive protein was identified as a predictor for heart failure." (PMID 39781722, 2025). "Studies have shown that statins reduce CRP levels, improve endothelial function, and decrease oxidative stress, making them a valuable adjunct to heart failure therapy in this population." (PMID 40787514, 2025). "In STEMI patients, elevated CRP levels serve as a reliable predictor of both heart failure and mortality." (PMID 41303859, 2025). "The predictors of mortality were high CRP levels at hospital admission and worsening of heart failure during treatment." (PMID 39330882, 2024). "The authors obtained 80.5% AUC with the model (Hb + serum creatinine + AST + hs-cTnI + CRP) created to differentiate between heart failure and chronic ischemic heart disease." (PMID 38633310, 2024). "In cases of severe heart failure, inflammation and difficulty absorbingnutrients result in significant changes in both CRP levels and serum albuminconcentrations." (PMID 39742221, 2024). "In addition, The Korean Heart Failure Registry, which included a large heterogeneous group of HF cases, demonstrated that CRP values on admission could help predict the risk of death 12 months after the index hospitalization, especially when combined with natriuretic peptide levels." (PMID 38541167, 2024). "Age, CRP levels, and anxiety act as independent predictors of frailty in patients with heart failure." (PMID 39685803, 2024). "In summary, the interaction between neutrophils, NET formation, and factors such as KLF2 and CRP is crucial in the progression and exacerbation of heart failure." (PMID 39130369, 2024). "Patients with hospitalization due to heart failure were more frequently smokers (78.0% vs 25.4%; p=0.031) and had higher C-reactive protein level (18.13 vs 7.52 mg/L; p=0.021)." (PMID 39114663, 2024). "In cases of heart failure, NETosis is regulated by inflammatory molecules such as C-reactive protein (CRP), and Krüppel-like factor 2 (KLF2) – a protein that plays a role in controlling inflammation, and angiotensin II." (PMID 39130369, 2024). "CRT has been shown to influence CRP levels in heart failure patients, increasing the benefits of the therapy itself by limiting inflammatory systemic processes." (PMID 39685924, 2024). "Many of the involved inflammatory markers, such as IL-6, CRP, TNF-α, IL-1β, and macrophage inhibitory factor (MIF), have been associated with post-MI hypertrophy, remodeling, persistent systolic dysfunction, heart failure, and mortality." (PMID 38558749, 2024).
heart failure (continued). "The independent predictors of mortality in our cohort were heart failure, low systolic blood pressure, respiratory rate, low oxygen saturation, elevated blood sugar, and elevated CRP." (PMID 39036024, 2024). "Patients with heart failure and higher levels of CRP have demonstrated an increased formation of NETs, which in turn can lead to aggravated vasculature injury and associated cardiovascular events." (PMID 39130369, 2024). "In restricted cubic spline curves, the rate of adverse events increased exponentially with higher C-reactive protein concentrations, plateauing at a C-reactive protein value of ≈5–6 mg/L for the outcome of heart failure." (PMID 39211962, 2024). "Third, the CRP levels at hospital admission and worsening of heart failure during treatment were independent predictors of death in the setting of CDIE." (PMID 39330882, 2024). "One patient had moderate pericardial effusion and severe heart failure (EF 20%) during the early acute phase of infection, with normal CRP." (PMID 39452295, 2024). "Interleukin-6 (IL-6), tumor necrosis factor-α (TNF-α), and CRP have been reported as serum inflammatory markers for heart failure." (PMID 39026227, 2024). "The initial evidence of C-reactive protein (CRP) elevation in heart failure (HF) can be traced back more than 60 years." (PMID 38540729, 2024). "Over the course of heart failure, a decrease incardiac output, myocardial hypoxia, and myocardial damage can trigger an upsurgein IL-6 production, which in turn raises CRP levels." (PMID 39742221, 2024). "Blood tests revealed higher levels of neutrophils, eosinophils, CRP and higher proportion of participants with heart failure or renal impairment." (PMID 39010888, 2024). "These predictors include older age, C-reactive protein levels at hospital admission, vegetation length at diagnosis, and the development of heart failure or embolic events during antimicrobial therapy." (PMID 39330882, 2024). "In summary, age, NIHSS score, dysphagia, atrial fibrillation, cardiac insufficiency, renal insufficiency, hepatic insufficiency, FBG, CRP, NEUT% and prealbumin were independent factors associated with the development of AP in AIS patients." (PMID 38034684, 2023). "A nomogram model incorporating age, NIHSS score, dysphagia, atrial fibrillation, cardiac insufficiency, renal insufficiency, hepatic insufficiency, FBG, CRP, NEUT%, and prealbumin effectively predicts AP risk in AIS patients." (PMID 38034684, 2023). "Another MR research on European populations in 2021 assesses the causative effects of 27 risk factors on the incidence and mortality of heart failure and reveals suggestive connections between genetically predicted CRP and heart failure incidence." (PMID 36882679, 2023). "In the second part of the study, we confirmed through ROC curves that CRP was a better predictor of early postoperative cardiac insufficiency outcomes (BNP level >400 pg/ml) than ESR and NLR, and we calculated an optimal CRP cut-off point of 5 mg/L." (PMID 37063874, 2023). "Alongside ‘classic’ cardiovascular biomarkers such as natriuretic peptides or highly sensitive C reactive protein, PICP was proven to have an important diagnostic and prognostic value in heart failure, predicting both cardiovascular and all-cause mortality." (PMID 36830758, 2023). "The correlation of heart failure and inflammation appears to be supported by the decrease in albumin concentration and the rise in other inflammatory biomarkers, such as C-reactive protein (CRP)." (PMID 36669034, 2023). "Patients with CRP levels >5 mg/L had a higher incidence of postoperative heart failure than other patients (20.7% vs. 12.6%, P<0.001), with a relative risk of 1.447 (95% confidence interval: 1.155–1.814)." (PMID 37063874, 2023). "In the Valsartan Heart Failure Trial (Val-HeFT), CRP was an independent predictor of mortality and morbidity in patients with established HF." (PMID 36882679, 2023).